CFI (complement factor I)
Diseases named in the same sentence as CFI in open-access papers (continued):
Sharing a sentence is not in itself a finding about the gene and the disease.
preeclampsia (3 papers, 2011 to 2025). Preeclampsia is a hypertensive disorder of pregnancy that is characterized by new-onset hypertension with proteinuria presenting after 20 weeks of gestation, and depending on mild or severe forms may initially present with severe headache, visual disturbances, and hyperreflexia. "We found identical heterozygous mutations in the gene encoding CFI in two unrelated white women with preeclampsia in the PROMISSE Study." (PMID 21445332, 2011). "MCP and CFI mutations are, to our knowledge, the first genetic defects to be associated with preeclampsia in pregnant patients with SLE and/or APL Ab." (PMID 21445332, 2011). "These patients have higher complement mutation frequency, including rare germline mutations in the alternative CS pathway (CFHR1, CFHR3, CFI, CFB, and CD46) than women with preeclampsia, having similar rates of variants as the control population." (PMID 40904461, 2025). "We identified heterozygous mutations in complement system pathway genes in seven of 40 patients with preeclampsia (18%)—four patients with mutations in MCP, two with CFI mutations, and one with a CFH mutation." (PMID 21445332, 2011). "We sequenced genes encoding three complement regulatory proteins—membrane cofactor protein (MCP), complement factor I (CFI), and complement factor H (CFH)—in 40 patients who had preeclampsia and found heterozygous mutations in seven (18%)." (PMID 21445332, 2011). "Identification of CFI I398L mutation, a complete loss of function leading to haploinsufficiency, supports a role for defects in complement regulation by CFI in the pathogenesis of preeclampsia." (PMID 21445332, 2011). "All patients with preeclampsia were screened for mutations in the genes encoding the complement regulatory proteins MCP, CFI, and CFH." (PMID 21445332, 2011). "Moreover, normal pregnant women (without SLE and APL Ab) with hypomorphic MCP and CFI genetic variants are more susceptible to developing preeclampsia than those without these variants." (PMID 40904461, 2025).
retinal degeneration (3 papers, 2017 to 2024). Degeneration of the retina. "GT005 aims to mitigate retinal degeneration caused by an overreactive complement system in the aging retina by increasing the expression of the complement factor I (CFI) protein, a gene addition strategy to reduce inflammation and alleviate the degeneration of retinal cells." (PMID 38565561, 2024). "The real-time RT-PCR was conducted to examine the expression of complement genes (C1q, C2, C3, C4, CFI and CFD) in the guinea pig model of long-term form deprivation-induced myopic retinal degeneration." (PMID 37448698, 2023).
Atrophy (2 papers, 2021 to 2022). Any weakening or degeneration, especially through lack of use. "Patients with high-risk complement factor I (CFI) alleles displayed a greater response to monthly lampalizumab with a 44% reduction (p = 0.0037) in GA atrophy progression compared to sham." (PMID 36009430, 2022). "Overexpression of CFI in the eye has the potential of restoring local complement activation accompanying AMD and thereby slowing down progression of atrophy." (PMID 33750925, 2021).
babesiosis (2 papers, 2023 to 2025). Babesiosis refers to a condition caused by microscopic parasites that infect the red blood cells. "Other identified proteins that differentiated uncomplicated from complicated babesiosis were various complement cascade components (CFI, CFP, C2, SERPING1, C8G), extracellular matrix components (TGFBI), acute phase proteins (ORM1, ITIH2, ITIH4, FGA, TF, RBP4) and lipoproteins (apoE)." (PMID 37353646, 2023).
C3 glomerulonephritis (2 papers, 2018 to 2021). "We have recently reported a patient with C3 glomerulonephritis (C3GN) and compound heterozygosity of two novel variations in the complement factor (CFI)." (PMID 34149444, 2021).
complement deficiencies (2 papers, 2018 to 2020). "Both rare monogenic traits, such as terminal complement deficiencies of C5-C9, CFD, CFB, CFI, and C3, and common polymorphisms in the CFH/CFHR3 region have been found in association with IMD." (PMID 32067109, 2020).
cutaneous vasculitis (2 papers, 2018 to 2022). Inflammation of the blood vessel wall characterized by palpable purpura. "Mast cells contribute to the pathogenesis of cutaneous vasculitis through complement C3 that is cleaved to C3b and then to iC3b by complement factor I. The receptor of iC3b, CD11b, is expressed on neutrophils and monocytes and CD14 on monocytes." (PMID 35747245, 2022).
glaucoma (2 papers, 2023 to 2024). Increased pressure in the eyeball due to obstruction of the outflow of aqueous humor. "However, eight proteins (C6, C8G, CFH, C3, CFHR1, CFI, CLU, and SERPING1) were significantly downregulated in Caucasian glaucoma subjects." (PMID 37763167, 2023).
glioma (2 papers, 2020 to 2025). A benign or malignant brain and spinal cord tumor that arises from glial cells (astrocytes, oligodendrocytes, ependymal cells). "Taken together, CFI was overexpressed in gliomas and associated with poor prognosis." (PMID 33614625, 2020). "JAK/STAT, NOD-like receptor, pathways in cancer, T cell receptor, and vascular endothelial growth factor (VEGF) were significantly enriched in the CFIhigh gliomas and therefore may be involved in mechanisms underlying CFI upregulation in glioma." (PMID 33614625, 2020). "Functional in vitro and in vivo assays further indicated that CFI knockdown suppressed glioma cell proliferation, invasion, and migration, whereas its overexpression had the opposite effects." (PMID 33614625, 2020). "To further explore the role of CFI in glioma progression in vivo, we injected luciferase-labeled control or shCFI U251 cells intracranially into 4-−6-week-old nude mice." (PMID 33614625, 2020). "To further establish an oncogenic role of CFI in glioma, we overexpressed the CFI gene in A172 cells and performed the same functional assays." (PMID 33614625, 2020). "Materials and Methods: The expression levels of CFI in glioma tissues and the survival of the CFIhigh and CFIlow patient groups were analyzed using The Cancer Genome Atlas (TCGA) database and Genotype-Tissue Expression (GTEx)." (PMID 33614625, 2020). "In the present study, we identified CFI as an independent prognostic factor of gliomas using integrated bioinformatics analyses." (PMID 33614625, 2020). "To further investigate the potential function of CFI in glioma, we conducted Gene Set Enrichment Analysis (GSEA) using the Kyoto Encyclopedia of Genes and Genomes (KEGG) sets (c2.cp.kegg.v6.2.symbols)." (PMID 33614625, 2020). "To summarize, integrated bioinformatics analysis showed that CFI is upregulated in gliomas and its expression level is correlated to the WHO tumor grade, IDH mutation status, and other clinical variables." (PMID 33614625, 2020). "Bioinformatics analyses also indicated a significant correlation of CFI expression level with several clinicopathological features and identified CFI as an independent prognostic indicator of OS in gliomas." (PMID 33614625, 2020). "We then stratified all glioma patients in TCGA database into the CFIhigh and CFIlow groups and found that CFI overexpression correlated to shorter OS in all gliomas." (PMID 33614625, 2020). "Taken together, CFI was significantly upregulated in glioma tissues and cell lines and correlated with worse prognosis in GBM patients, indicating its potential as a prognostic biomarker." (PMID 33614625, 2020). "Our findings provide novel molecular insights into glioma progression and recognize CFI as a promising prognostic biomarker and therapeutic target for glioma." (PMID 33614625, 2020). "CFI knockdown in glioma cell lines inhibited growth in vitro and in vivo, whereas its ectopic expression increased glioma cell proliferation, migration, and invasion in vitro." (PMID 33614625, 2020). "Consistent with this, knocking down CFI also markedly reduced the number of colonies formed by the glioma cells." (PMID 33614625, 2020). "The correlation between CFI expression in gliomas and the clinicopathological features were next analyzed in the CGGA dataset." (PMID 33614625, 2020). "CFI was highly expressed in glioma cell lines and tissues, and its knockdown significantly inhibited glioma cell proliferation, migration, and invasion in vitro and in vivo." (PMID 33614625, 2020). "The western blotting results were confirmed by immunohistochemistry, and the glioma tissues showed significantly higher in situ expression of CFI compared to the NBTs." (PMID 33614625, 2020). "Nevertheless, silencing CFI in the glioma cells significantly decreased their proliferation, invasion, and migration abilities, whereas its ectopic expression had the opposite effect." (PMID 33614625, 2020).
glioma (continued). "Consistent with this, high CFI expression level also predicted worse prognosis for all glioma patients in the CGGA database." (PMID 33614625, 2020). "CFI protein levels were also significantly higher in the glioma tissues resected from patients and correlated to worse prognosis." (PMID 33614625, 2020). "Taken together, CFI serves as an independent prognostic biomarker in glioma and contributes to tumor malignant progression." (PMID 33614625, 2020). "CFI was also significantly upregulated in glioma cell lines and tumor tissues, and its ectopic expression enhanced the invasion, migration, and proliferation of tumor cells in vitro." (PMID 33614625, 2020). "In this study, we found that CFI is significantly upregulated in glioma tissues and strongly correlated with the prognosis of glioma patients in TCGA and CGGA cohorts." (PMID 33614625, 2020). "The correlation between CFI expression and clinicopathological features of glioma was determined by univariate and multivariate Cox regression analyses in the Chinese Glioma Genome Atlas (CGGA) database." (PMID 33614625, 2020). "Collectively, these results suggest that downregulation of CFI effectively inhibits cell proliferation, invasion, and migration of glioma cells." (PMID 33614625, 2020). "The aim of our study was to evaluate the prognostic significance and function of the complement factor I (CFI) in glioma." (PMID 33614625, 2020). "The control mice exhibited tumor growth over 21 days after inoculation, whereas the CFI-depleted glioma cells formed significantly smaller tumors." (PMID 33614625, 2020). "Together, CFI overexpression induced proliferation, invasion, and migration in glioma cells, indicating that the gain of function of CFI likely enhances their malignant potential." (PMID 33614625, 2020). "To determine whether inhibition of CFI can affect glioma development, we analyzed the proliferation, migration, and invasion capacities of the CFI-knockdown cells in vitro." (PMID 33614625, 2020). "CFI protein level increased through glioma grades I–II, III, and IV compared to the NBTs." (PMID 33614625, 2020). "The functional role of CFI in glioma was established through routine in vitro and in vivo assays." (PMID 33614625, 2020). "Furthermore, we tried to investigate the expression and prognostic value of CFI in glioma subgroups in the CGGA dataset according to WHO 2016 classification." (PMID 33614625, 2020). "Together, inhibition of CFI impedes glioma growth in vivo, indicating its therapeutic potential." (PMID 33614625, 2020). "Therefore, we next evaluated the effect of CFI knockdown on the invasion and migration of glioma cells through transwell and wound healing assays, respectively." (PMID 33614625, 2020). "Furthermore, glioma samples with IDH mutation or 1p/19q co-deletion expressed lower levels of CFI compared to the corresponding non-mutated samples." (PMID 33614625, 2020). "In addition, we identified CFI as an independent prognostic factor of OS in glioma patients." (PMID 33614625, 2020). "However, since CFI expression alone is insufficient to evaluate survival, we constructed a nomogram incorporating the seven independent prognostic factors to quantitatively estimate the 1-, 3-, and 5-year OS possibility of patients with glioma." (PMID 33614625, 2020). "Furthermore, CFI was identified as an independent prognostic factor of glioma in the CGGA database." (PMID 33614625, 2020). "Thus, CFI likely functions as an oncogene in glioma and promotes tumor progression." (PMID 33614625, 2020). "To gain further insights into the role of CFI in gliomas, we knocked down its expression in U251 and LN229 glioma cell lines using three independent lentiviral shRNAs." (PMID 33614625, 2020). "We identified CFI as a potential biomarker of glioma on the basis of bioinformatics analysis and the differential expression between gliomas and corresponding normal tissue samples (data not shown)." (PMID 33614625, 2020).
glioma (continued). "The CFI expression was significantly elevated in IDH wildtype grade II glioma, IDH mutant and 1p/19q non-codeleted grade III glioma, and IDH wildtype GBM compared to corresponding control groups." (PMID 33614625, 2020).
meningoencephalitis (2 papers, 2017 to 2023). Inflammation of the meninges and brain, generally secondary to an infectious cause. "The deficit of complement factor I (CFI) is frequently associated with recurrent pyogenic infections such as meningitis and meningoencephalitis." (PMID 28676848, 2017). "A 32-year-old woman who had been admitted to an emergency department with presumed meningoencephalitis, and who had had several prior episodes of coma, was found to have biallelic variants in CFI, indicating a non-classical presentation of Complement Factor I deficiency." (PMID 37946251, 2023).
myopia (2 papers, 2016 to 2023). "In this study, we detected significantly higher intraocular levels of complement proteins involved in the classic pathway (C1q, C2, C4 and C4b) and alternative pathway (CFB, CFI, C3b/iC3b) in human eyes with high-myopia or with pathological myopia." (PMID 37448698, 2023). "Furthermore we conducted a meta-analysis of COL8A1, CFI and LIPC genes SNPs (rs669676, rs10033900 and rs10468017) and found that only rs669676 of these SNPs were associated with high myopia neovascularization." (PMID 27643879, 2016).
primary immunodeficiency (2 papers, 2012 to 2025). "Complement factor I (CFI) deficiency is a rare primary immunodeficiency that disrupts the classical and alternative complement pathways, potentially causing severe recurrent infections and autoimmune manifestations in pediatric patients." (PMID 40196760, 2025). "Deficiency of Complement Factor I (CFI, OMIM*217030) is a very rare primary immunodeficiency disease, inherited as an autosomal recessive trait." (PMID 22710145, 2012).
uveitis (2 papers, 2017 to 2023). An inflammatory process affecting a part of or the entire uvea. "Of these, variants in CFH, CFB and CFI involved in the alternative complement pathway, were identified as genetic risk factors for uveitis and specific subtypes." (PMID 28408754, 2017).
acute disseminated encephalomyelitis (1 paper, 2020). Acute disseminated encephalomyelitis (ADEM) is a demyelinating disorder of the central nervous system. "We report a case of life-threatening, nonhemorrhagic fulminant CNS inflammation, radiologically resembling acute disseminated encephalomyelitis (ADEM), in association with complete complement factor I (CFI) functional deficiency." (PMID 32098865, 2020).
acute renal failure (1 paper, 2012). "Heterozygous CFI mutations are associated with atypical haemolytic uremic syndrome (aHUS), a severe disorder characterized by thrombocytopenia, microangiopathic haemolytic anaemia and acute renal failure." (PMID 22710145, 2012).
autoimmune disease (1 paper, 2022). A disorder resulting from loss of function or tissue destruction of an organ or multiple organs, arising from humoral or cellular immune responses of the individual to their own tissue constituents. "Given the crucial role in balancing complement activation, CFI is considered a vital target for pharmaceutical control in many complement-mediated autoimmune diseases in mammals." (PMID 36232671, 2022).
Autoimmunity (1 paper, 2018). The occurrence of an immune reaction against the organism's own cells or tissues. "Therapeutic options for autoimmunity/autoinflammation associated with CFI deficiency are limited." (PMID 29696024, 2018).
B-cell CLL (1 paper, 2022). "A total of 16 GO terms were enriched for down-regulated NSDEGs, including cfi (complement factor I) and bcl10 (B-cell CLL/lymphoma 10), and the most significant GO term was “MHC class II protein complex” related to immune response." (PMID 35669183, 2022).
co-infection (1 paper, 2022). "Herein, we report a case of an HIV-negative Chinese man with a severe, disseminated co-infection of Talaromyces marneffei and Mycobacterium tuberculosis, who had a high-titer of anti IFN-γ autoantibodies and a CFI heterozygous nonsense gene mutation." (PMID 35090402, 2022).
Cognitive impairment (1 paper, 2013). Abnormal cognition is characterized by deficits in thinking, reasoning, or remembering. "Although these core genes like C9 and CFI were from Pattern 2 which was related to sensory function, the immunological roles of these genes imply that immune functions could be critical on cognitive impairment by BCCAO." (PMID 23936146, 2013).
colon carcinoma (1 paper, 2022). "Also, in colon carcinoma tissues, multiple complement elements including C2, C5, complement factor B (CFB), complement factor I (CFI), CR4, complement component 4 binding protein (C4BPB), CD46, CD55, and CPN1 were significantly higher than that in normal tissues." (PMID 35173724, 2022).
end-stage renal disease (1 paper, 2014). "Another report described two patients with Stx-HUS resulting in end-stage renal disease (ESRD) who developed recurrent HUS following renal transplantation and were subsequently found to have complement gene mutations (CFI; p.V412M, MCP IVS2+2 T>G)." (PMID 24944786, 2014).
epilepsy (1 paper, 2016). A brain disorder characterized by episodes of abnormally increased neuronal discharge resulting in transient episodes of sensory or motor neurological dysfunction, or psychic dysfunction. "Thus, the down-regulation of CFI may promote the activation of complements to accelerate the progression of epilepsy." (PMID 26742644, 2016). "Taken together, we proposed that complement system might play key roles in the development of epilepsy by dysregulating the expression of C1QB, C1S and CFI." (PMID 26742644, 2016). "The dysregulation of C1QB, C1S, CFI, SCN3B and FN1 may be used potential gene targets for epilepsy treatment." (PMID 26742644, 2016). "Additionally, C1QB, C1S, CFI, SCN3B and FN1 may be potential therapeutic targets for epilepsy." (PMID 26742644, 2016).
fungal infection (1 paper, 2020). "The presence of negative regulators, CFH and CFI, in the patient tear indicate that the complement activity is tightly regulated during fungal infection." (PMID 32435625, 2020).
gallstones (1 paper, 2023). Solid crystalline precipitates in the biliary tract, usually formed in the gallbladder, resulting in the condition of cholelithiasis. "Consistent with the proteomic quantitation results, the expression of CFI remained constant between polyp and gallstone bile samples, while C5 was found to be increased in gallstone bile samples." (PMID 38111640, 2023).
Hernia (1 paper, 2021). "The CFI gene, like the MAP1LC3C, was upregulated in animals with hernia when compared to the control group." (PMID 33513662, 2021).
Immunodeficiency (1 paper, 2019). Failure of the immune system to protect the body adequately from infection, due to the absence or insufficiency of some component process or substance. "Deficiency of complement factor I is a rare immunodeficiency that typically presents with increased susceptibility to encapsulated bacterial infections." (PMID 31231365, 2019).